L3MBTL4 (L3MBTL histone methyl-lysine binding protein 4)
Description:
Putative Polycomb group (PcG) protein. PcG proteins maintain the transcriptionally repressive state of genes, probably via a modification of chromatin, rendering it heritably changed in its expressibility (By similarity).
Synonyms: FLJ35936; HsT1031
Tractability: PROTAC: a small molecule that binds it is known.
Target class: Methyl-lysine/arginine binding protein; MBT domain; Epigenetic regulator; Reader
Gene: Protein-coding gene on chromosome 18 (5,952,760 to 6,415,477, reverse strand). Ensembl gene ENSG00000154655.
Subcellular location: Nucleus
Subcellular location (Human Protein Atlas): Nucleoplasm; Vesicles
Gene Ontology:
Molecular function: protein binding; chromatin binding; histone binding; zinc ion binding
Biological process: negative regulation of DNA-templated transcription; regulation of DNA-templated transcription
Cellular component: nucleus
Genetic constraint (gnomAD): Loss-of-function variants: 21 observed, 38.15 expected, observed/expected ratio (o/e) 0.55, 90% interval 0.39 to 0.79. The upper end of that interval is the gene's LOEUF score, 0.79, which puts it in group 3 of 6, group 1 being the genes least tolerant of losing a copy. Missense variants: 342 observed, 387.1 expected, observed/expected ratio (o/e) 0.88, 90% interval 0.81 to 0.97. Synonymous variants: 143 observed, 140.56 expected, observed/expected ratio (o/e) 1.02, 90% interval 0.89 to 1.17.
Homologues: Orthologues: chimpanzee L3MBTL4 (99% identical), macaque L3MBTL4 (97% identical), dog L3MBTL4 (92% identical), rabbit L3MBTL4 (84% identical), mouse L3mbtl4 (81% identical), rat L3mbtl4 (80% identical), Drosophila melanogaster l(3)mbt (19% identical), Drosophila melanogaster Sfmbt (15% identical), Caenorhabditis elegans lin-61 (15% identical), Caenorhabditis elegans mbtr-1 (13% identical). Paralogues in human: L3MBTL3 (50% identical), L3MBTL1 (46% identical), SCML2 (23% identical), SCMH1 (22% identical), SFMBT1 (19% identical), SFMBT2 (19% identical), L3MBTL2 (18% identical), MBTD1 (16% identical), PHC2 (16% identical), PHC1 (15% identical), PHC3 (15% identical), SAMD11 (14% identical), and 6 more.
Diseases named in the same sentence as L3MBTL4 in open-access papers:
L3MBTL4 is named in the same sentence as 25 diseases in open-access papers, as found by Europe PMC text mining. Sharing a sentence is not in itself a finding about the gene and the disease. The quoted sentences say what the papers report.
breast carcinoma (4 papers, 2010 to 2024). "Single- and double-strand deletions of L3MBTL2 and L3MBTL3 were found in medulloblastoma whereas L3MBTL4 has mutations or deletions in breast cancer." (PMID 39231972, 2024). "First, it lies within the region of chromosome 18 that is frequently deleted in breast cancers; L3MBTL4 is also targeted by mutations and breakages and is dowregulated in tumors." (PMID 20698951, 2010). "To document the involvement of L3MBTL4 in breast cancer we searched for mutations by sequence analysis of 180 primary tumor samples and 47 cell lines." (PMID 20698951, 2010). "This suggests that L3MBTL4 loss occurs specifically in breast cancers." (PMID 20698951, 2010). "Thus, the L3MBTL4 gene is targeted by various genomic alterations, including loss and breakage, in a high proportion of breast cancers." (PMID 20698951, 2010). "Among the 340 under-expressed genes containing the 586 hyper-methylated CpGs, there were several tumor suppressor genes with under-expression that has previously been observed in breast cancer, such as L3MBTL4, ID4, RUNX3, PROX1, SFRP1 and others." (PMID 27386846, 2016). "Expression of L3MBTL4 level was decreased at least two-fold in 73% of breast cancer samples, particularly in tumors deleted at the L3MBTL4 locus since decreased expression correlated with genomic alteration." (PMID 20698951, 2010). "Interestingly, L3MBTL4 is centromeric and in close proximity to the loss of heterozygosity (LOH) region spanning EPB41L3 previously reported in non-small cell lung carcinomas, breast carcinomas, and meningiomas." (PMID 20698951, 2010). "This suggests that L3MBTL4 does not play a TSG role in this subtype of breast cancer." (PMID 20698951, 2010).
breast tumors (4 papers, 2010 to 2023). "We also identify a novel candidate hard sweep within L3MBTL4, an apparent tumor suppressor gene that is often mutated, downregulated, or deleted in breast tumors." (PMID 26977894, 2016). "Few cases displayed mRNA downregulation in the absence of loss suggesting that other mechanisms such as epigenetic repression play a role in the downregulation of L3MBTL4 in breast tumors." (PMID 20698951, 2010). "L3MBTL4 mRNA expression is low in non-basal breast tumors and in particular in tumors with loss of the gene." (PMID 20698951, 2010). "Comparison of clinical features between breast tumors with and without L3MBTL4 loss showed that L3MBTL4 loss was associated with the presence of lymph node metastases (p = 1.02 10-2), high SBR grade (p = 1.15 10-2) and luminal B molecular subtype defined by SSP classification (p = 3.10-5)." (PMID 20698951, 2010). "A study reported the reduced L3MBTL4 gene expression in non-basal breast tumors." (PMID 37007972, 2023).
cardiac hypertrophy (2 papers, 2016 to 2020). "Our finding that L3MBTL4 over-expression results in increased BP and heart hypertrophy supports a pathogenic role for L3MBTL4 in the context of hypertension that extends beyond its putative function as a tumor suppressor." (PMID 27480026, 2016). "Then, we identified that L3MBTL4 is predominantly expressed in VSMCs, and L3MBTL4 TGs exhibited remarkable elevated BP, vascular remodeling, and cardiac hypertrophy." (PMID 33381308, 2020). "Rats with ubiquitous over-expression of L3MBTL4 exhibited significantly elevated BP, increased thickness of the vascular media layer and cardiac hypertrophy." (PMID 27480026, 2016). "Furthermore, rats over-expressing L3MBTL4 exhibited significantly elevated BP and cardiac hypertrophy." (PMID 27480026, 2016).
Hypertension (2 papers, 2016 to 2020). The presence of chronic increased pressure in the systemic arterial system. "For the purpose of identifying novel variants contributed to hypertension, our previous genome-wide association study was performed and pinpointed L3MBTL4 as the new gene significantly associated with hypertension." (PMID 33381308, 2020). "Consistent with our results, overexpression of hypertension susceptibility gene L3MBTL4 promoted the VSMCs proliferation, migration, and transformation to synthetic type." (PMID 33381308, 2020). "Our previous work has identified L3MBTL4 as a novel susceptibility gene for the development of essential hypertension, accompanied with activation of p38/JNK." (PMID 33381308, 2020). "We first report a genome-wide significant locus in L3MBTL4 gene (rs403814) and comprehensively illustrate its pathogenic effects and probable mechanisms as a potential inducer of hypertension." (PMID 27480026, 2016). "Of note, our previous GWAS study has identified that a genome-wide significant locus in L3MBTL4 was strongly associated with essential hypertension and verified that L3MBTL4 is predominantly expressed in vascular smooth muscle cells (VSMCs) and contributed to elevated BP and vascular remodeling." (PMID 33381308, 2020). "To investigate whether L3MBTL4 participates causally in the development of hypertension, we constructed L3MBTL4 transgenic rats (TGs) and confirmed increased L3MBTL4 expression, at both the mRNA and protein levels in the vasculature." (PMID 27480026, 2016). "Our findings pinpointed that p38 and JNK were required for the proliferation and phenotype changes of VSMCs induced by L3MBTL4 in hypertension." (PMID 33381308, 2020). "What is more, we identified that phosphorylation of p38/JNK is the pivotal step mediating L3MBTL4-induced hypertension." (PMID 33381308, 2020). "According to the results from application of inhibitors of p38/JNK, we found that p38/JNK was required for L3MBTL4 to play the role in promoting the progression of hypertension and propelling VSMCs proliferation and phenotype alteration." (PMID 33381308, 2020). "The present study characterized that p38/JNK was required for the proliferation and phenotype alteration of VSMCs mediated by L3MBTL4 in hypertension." (PMID 33381308, 2020). "We confirmed that p38/JNK was required for phenotype changes of VSMCs induced by L3MBTL4 in hypertension." (PMID 33381308, 2020). "To further understand the biological and cellular functions of L3MBTL4, especially within the context of hypertension, we performed a number of functional studies." (PMID 27480026, 2016). "To determine the expression and distribution of L3MBTL4 in hypertension, we performed q-PCR and Western blotting, and compared L3MBTL4 mRNA and protein expression from different tissues of SHRs, the most widely-used animal model for hypertension, and WKYs, a normotensive reference group." (PMID 27480026, 2016). "Thus LTBP1 is responsible for the activation of MAPKs, and repressed LTBP1 may be a primary factor in the effect of L3MBTL4 on vascular remodeling and hypertension." (PMID 27480026, 2016). "Thus, we conferred that L3MBTL4 gene might be a potential induce factor for hypertension." (PMID 33381308, 2020). "These novel findings yield new insights into the genetic and biological basis of hypertension and are fundamental for further studies to explore the intervention strategies targeting L3MBTL4 and p38/JNK to counteract the progression of hypertension." (PMID 33381308, 2020).
malignant brain tumor (2 papers, 2010 to 2023). "The L3MBTL4 protein contains three "malignant brain tumor" (MBT) domains." (PMID 20698951, 2010). "The malignant brain tumor (MBT) family is a large family with L3MBTL1, L3MBTL2, L3MBTL3, L3MBTL4, and other members." (PMID 38201555, 2023).
Bardet-Biedl syndrome (1 paper, 2024). A ciliopathy with multisystem involvement. "The L3MBTL4 gene has been linked to N Syndrome, which can cause seizures, nystagmus, spasticity, and severe intellectual impairment, and Bardet–Biedl Syndrome, which often presents with visual and intellectual impairments." (PMID 39062924, 2024).
Dysmenorrhea (1 paper, 2022). Pain during menstruation that interferes with daily activities. "These SNPs mapped closely to L3MBTL4 which encodes the histone methyl-lysine binding protein and was genome-wide significant in a GWAS of pain severity in dysmenorrhea, a pain syndrome in women characterized by pain with menses." (PMID 35401282, 2022).
left ventricular hypertrophy (1 paper, 2020). Enlargement of the LEFT VENTRICLE of the heart. "In L3MBTL4 transgenic rats, we found that the elevated blood pressure, increased left ventricular hypertrophy, and thickened vascular media layer were significantly relieved by both p38 and JNK inhibitors." (PMID 33381308, 2020). "According to the pivotal role of p38/JNK in L3MBTL4-mediated elevated BP, left ventricular hypertrophy, and vascular remodeling, we further focused on VSMCs, the most prominent cellular constituent of blood vessel." (PMID 33381308, 2020).
lymph node metastasis (1 paper, 2010). "L3MBTL4 loss was associated with high grade and with lymph node metastasis." (PMID 20698951, 2010). "Finally, we found that L3MBTL4 deletions correlate with low mRNA expression and with the presence of lymph node metastasis, high Scarf-Bloom-Richardson (SBR) grade and luminal B molecular subtype." (PMID 20698951, 2010).
tumor (11 papers, 2010 to 2023). "It was reported that loss, mutation, and deregulation of L3MBTL4 was associated with human breast cancer and identified as the potential tumor suppressor gene." (PMID 33381308, 2020). "In tumor T8700 loss within 18p11.31 spanned the L3MBTL4 gene only." (PMID 20698951, 2010). "In our analysis, L3MBTL4 (histone methyl-lysine binding protein 4) gene, which is known as a tumor suppressor gene, is identified as another potentially important gene for the classification of Luminal and ER-negative groups." (PMID 37007972, 2023). "We also determined L3MBTL4 gene expression in 229 tumor samples and 4 NB samples by using Affymetrix microarrays." (PMID 20698951, 2010). "L3MBTL4 was targeted by copy number transition in tumor T50115, and in the HCC38 and MDA-MB-453 cell lines." (PMID 20698951, 2010). "Furthermore, L3MBTL4 was identified as a tumor suppressor gene in myeloid malignancies and neuroblastoma either." (PMID 33381308, 2020). "L3MBTL4 is a potential tumor suppressor gene in chromosome arm 18p." (PMID 31993418, 2019). "Overall, tumor samples expressed a low level of L3MBTL4 mRNA as compared with normal breast tissue." (PMID 20698951, 2010). "Of the promoters gaining methylation in our sample, many have already been shown to have tumour suppressor activity, including RORa, FAN1, PRDM1, CYGB, L3MBTL4, EPB41L3, with ZNF471 and ZNF671 being specifically silenced by methylation." (PMID 31357948, 2019). "The deleted 18p11.21 region contains important tumor inhibitory genes, for example EPB41L3, L3MBTL4, ARHGAP28, PTPRM, and ROCK1 (for complete list of genes in deletion regions)." (PMID 22363777, 2012). "We studied the exon sequence of L3MBTL4 in 180 primary tumor samples and 47 cell lines and found six missense and one nonsense heterozygous mutations." (PMID 20698951, 2010).
cancer (4 papers, 2010 to 2017). A tumor composed of atypical neoplastic, often pleomorphic cells that invade other tissues. "Alteration of L3MBTL4, coding for a regulator of epigenetic marks, is well in line with recent advances in cancer research." (PMID 20698951, 2010). "Third, L3MBTL4 has three paralogs that are suspected to play a role in the etiology of certain types of cancer." (PMID 20698951, 2010). "Interestingly, L3MBTL4, a methyl-lysine reader, is one of the most repressed chromatin factors across all cancer types examined." (PMID 25484917, 2014). "In this scenario, the vast majority of CpG island promoter methylated genes represent passenger events with only a few true cancer driving events found in each case; in this context, DZIP1, COL4A2, L3MBTL4, IRX1 and RASSF10 are named as likely candidates." (PMID 25468711, 2015). "Taken together, our results suggest that aberrations targeting L3MBTL4 could confer to cancer cells specific advantages but do not exclude the role of other potential 18p candidates." (PMID 20698951, 2010).
L3MBTL4 also shares sentences with these, for which no sentence is quoted: Autoimmunity (1 paper); colon cancers (1); essential hypertension (1); intellectual impairments (1); medulloblastoma (1); meningioma (1); N syndrome (1); neurological diseases (1); non-small cell lung carcinoma (1); Nystagmus (1); sarcoma (1); thoracic aortic aneurysm (1); thyroid disease (1); tobacco use disorder (1).